HDAC2 (histone deacetylase 2)
Diseases named in the same sentence as HDAC2 in open-access papers (continued):
Sharing a sentence is not in itself a finding about the gene and the disease.
pancreatic cancer (26 papers, 2010 to 2025). "High levels of HDAC1 and HDAC2 expression are linked to distant pancreatic cancer transitions, and both proteins enhance tumor invasiveness." (PMID 36902253, 2023). "The STA inhibits the HDAC2/β-catenin signaling pathway and suppresses the migration and invasion of pancreatic cancer cells." (PMID 40050614, 2025). "mRNA expression of HDAC2 and level of inflammatory cytokines were reduced in the spinal tissue of 5HT 2A antagonist treated group than pancreatic cancer group of mice." (PMID 38629654, 2024). "Transcriptional activation of the pro-apoptotic sensor NOXA by HDACi occurs in pancreatic cancer and can be achieved by selective inhibition of HDAC2." (PMID 37509312, 2023). "The epigenetic eraser histone deacetylase 2 (HDAC2) has previously been shown to be connected to undifferentiated pancreatic cancer." (PMID 35158814, 2022). "ZEB1 regulates the recruitment of HDAC1 and HDAC2 to the CHD1 promoter in human pancreatic cancer cells." (PMID 32210140, 2020). "Myc is well appreciated as an oncogene that has been shown to induce HDAC2 (a major target of entinostat) in colorectal and pancreatic cancer; therefore, we sought to experimentally validate the role of Myc signaling in sensitivity to entinostat." (PMID 30497520, 2018). "With more investigations, the involvement of HDAC7/HDAC2/Nur77 in the pathogenesis of pancreatic tumors can be clarified." (PMID 25275504, 2014). "ARHGAP4 regulates HDAC2 degradation by ubiquitination and enhances the expression of the Wnt/β-catenin signal pathway by regulating β-catenin activation, thus promoting the invasion and metastasis of pancreatic cancer." (PMID 38087046, 2024). "Recent studies have demonstrated the role of HDAC2 in facilitating pancreatic cancer metastasis." (PMID 38798691, 2024). "In addition, class I HDACs promote the epithelial-to-mesenchymal transition (EMT) of pancreatic tumor cells via the Snail/HDAC1/HDAC2 complex, which subsequently suppresses E-Cadherin expression." (PMID 35327319, 2022). "In addition, HDAC2 was found to positively regulate Aurora A kinase, which induces pancreatic cancer cell growth and inhibits the cells death via inducing ciliary loss." (PMID 32210140, 2020). "In addition to the HDAC1/HDAC2-dependent transcriptional regulation of MYC in pancreatic carcinoma cells, our data collected with RGFP966 suggest that HDAC3 supports the expression of MYC in leukemic cells." (PMID 31561534, 2019). "Furthermore, both N-MYC and c-MYC were found to upregulate HDAC2 expression in neuroblastoma and pancreatic cancer, respectively, which contributed to MYC-induced tumor cell proliferation and blocked apoptosis in these models." (PMID 28505071, 2017). "Additionally, ZEB1 can down-regulate E-cadherin expression via recruiting histone deacetylases HDAC1 and HDAC2 in pancreatic cancer." (PMID 26036631, 2015). "Moreover, snail mediates E-cadherin repression by the recruitment of the HDAC1/2 complex and E-cadherin is suppressed by a snail/HDAC1/HDAC2 complex to regulate metastasis of pancreatic cancer." (PMID 26336990, 2015). "We also performed a Kaplan-Meier survival analysis, which revealed that the higher expression of HDAC1, HDAC2, HDAC7, and HDAC9 led to poor overall survival in pancreatic cancer patients." (PMID 39123441, 2024). "Pancreatic cancer cells proliferate and migrate more readily because of HDAC1 and HDAC2-mediated inhibition of E-cadherin expression in tumor cells." (PMID 36902253, 2023).
pancreatic cancer (continued). "MYC and HDAC2 repress Cyclin G2 (CCNG2), which ordinarily blocks the progression of the cell cycle, in neuroblastoma and pancreatic cancer cells to drive proliferation." (PMID 28505071, 2017). "Class I HDACs are important regulators of apoptosis and cell cycle, e.g., HDAC2 induces epigenetic silencing of the pro-apoptotic NOXA gene, whereas HDAC2 inhibition sensitized pancreatic tumor cells for tumor necrosis factor-related apoptosis-inducing ligand (TRAIL)-induced apoptosis." (PMID 35327319, 2022). "Furthermore, HDAC2 contributes to EMT, one initial mechanism of metastasis, by the downregulation of E-cadherin in pancreatic cancer cells." (PMID 20398369, 2010). "Depletion of HDAC2, but not HDAC1, in the pancreatic cancer cell lines MiaPaCa2 and Panc1 resulted in a marked sensitization towards the tumor necrosis factor-related apoptosis-inducing ligand (TRAIL)." (PMID 20398369, 2010).
Alzheimer disease (21 papers, 2014 to 2026). A progressive, neurodegenerative disease characterized by loss of function and death of nerve cells in several areas of the brain leading to loss of cognitive function such as memory and language. "Restoring miR-101b levels or inhibiting AMPK can reverse tau pathology and dendritic abnormalities caused by HDAC2 overexpression, both in vitro and in an Alzheimer’s disease mouse model." (PMID 40940748, 2025). "Elevated HDAC2 levels are also associated with tau hyperphosphorylation, aggregation, and dendritic abnormalities in Alzheimer’s disease." (PMID 40940748, 2025). "Grin2a expression was previously linked to HDAC2 activity and H4K12acetylation in animal models of Alzheimer’s disease." (PMID 29089052, 2017). "Human histone deacetylase 2 (HDAC2) has been identified as being associated with Alzheimer's disease (AD), a neuropathic degenerative disease." (PMID 25045700, 2014). "Dysregulation of HDAC2 has been implicated in neurodegenerative disorders including Alzheimer’s Disease (AD), where it may contribute to cognitive impairment." (PMID 33802405, 2021). "For example, genetic knockdown of Hdac2 expression by 25–30% increased transcription of memory-related genes and synaptic protein density, rescued long-term potentiation, and improved associative and spatial memory in an Alzheimer’s disease rodent model." (PMID 31270332, 2019). "These evidences indicate that allelic differences in rs2427556 of mir-941-1 and HDAC2 might play important roles in cognitive impairment associated diabetes mellitus, also known as type 3 diabetes and was observed in cases of Alzheimer’s disease." (PMID 26053627, 2015). "Inhibition of HDAC2 is beneficial in the amelioration of neurodegenerative pathologies in Alzheimer’s disease (AD), Parkinson’s disease (PD), and ischemic stroke." (PMID 39682714, 2024). "In Alzheimer's disease tissues and models, the interactions between Sp3 and HDAC2 regulate synaptic plasticity via repression of multiple transcripts involved in synapse formation." (PMID 36762637, 2023). "According to a literature, HDAC2 overexpression contributes to the deacetylation of the hepatocyte nuclear factor 4α (HNF4A) transcription factor during Alzheimer's disease." (PMID 34586697, 2021). "HDAC2 is known to participate in memory impairment, and hyperexpression of HDAC2 is involved in neurodegenerative disorders such as Alzheimer’s disease." (PMID 31796106, 2019). "Additionally, epigenetic modulation which includes histone deacetylase 2 (HDAC2) alteration is considered as a pivotal factor in Alzheimer’s disease (AD) pathogenesis." (PMID 38765810, 2024). "Expression of the epigenetic regulator HDAC2 is altered in neurodegenerative diseases such as Alzheimer’s disease and this may influence expression of genes related to cognition." (PMID 33802405, 2021). "Importantly, it was depicted in a prior research that HDAC2 overexpression augmented the deacetylation of HNF4A during Alzheimer's disease, which partially supported our results that HDAC2 repressed HNF4A expression through deacetylation during endometriosis." (PMID 34586697, 2021). "Increased HDAC2 expression is observed in the prefrontal cortex during the human aging process and its overexpression constitutes an early pathological event in Alzheimer’s disease (AD)." (PMID 30377985, 2019). "Interestingly, levels of HDAC2 were found to be increased by neurotoxic insults in vitro in two mouse models of neurodegeneration, and in patients with Alzheimer’s disease." (PMID 24576665, 2014). "Our bioinformatics analysis revealed four key differential genes—ASS1, HDAC2, SIRT3, and VEGFA—as Co-DEGs in patients with Alzheimer’s disease (AD) and OSA." (PMID 39081807, 2024). "Deletion of HDAC1 and HDAC2 in microglia (but not other cell types) reduces amyloid load and improves cognitive function in Alzheimer’s disease models by enhancing microglial amyloid phagocytosis." (PMID 40940748, 2025).
depression (20 papers, 2017 to 2025). "Glial cell-derived neurotrophic factor (Gdnf) is one of the candidate target genes for HDAC2 associated with stress and depression." (PMID 34276306, 2021). "Decreased HDAC2 protein expression in the nucleus accumbens was also associated with both depression in humans and chronic stress-like behavior in mice." (PMID 33071792, 2020). "The imbalance of HDAC2 is associated with diseases such as schizophrenia, affective disorder, and depression." (PMID 32499679, 2020). "Consistently, increased HDAC2 protein level in the hippocampus of a mouse model of depression is associated with cognitive decline." (PMID 30377985, 2019). "In order to evaluate how the HDAC2 forebrain KO matched human depression, a subset of highly connected congruent genes (up-up or down-down) were plotted in STRING." (PMID 34997033, 2022). "Generally, in these animal models of depression, HDAC2 and HDAC5 were elevated in the Hp but decreased in the nucleus accumbens." (PMID 35011254, 2021). "Mice overexpressing HDAC2 in the nucleus accumbens exhibit more depression-like behavior, and HDAC inhibitor was shown to ameliorate the depression-like behavior associated with exposure to chronic stress." (PMID 34276306, 2021). "In the corticosterone (CORT) model of depression, HDAC2 was significantly elevated, while fluoxetine and vorinostat normalized their levels." (PMID 35011254, 2021). "Previously, it was shown a decline in the HDAC2 protein in the nucleus accumbens (NAc) in clinical depression." (PMID 32970734, 2020). "The NAc is implicated in depression, and abnormal expression of HDACs such as HDAC5 and HDAC2 has been observed in the NAc." (PMID 33574772, 2020). "It has been reported that HDAC2 expression is significantly up-regulated in patients with depression." (PMID 32499679, 2020). "Increased HDAC2 protein level was observed in the hippocampus of a mouse model of depression, but reduced HDAC2 expression was observed in the nucleus Accumbens (NAc) of another depressive rodent model as well as in postmortem NAc samples of MDD patients." (PMID 30377985, 2019). "Seven models that matched depression from different approaches (HDAC2 forebrain KO, APPsa knockin, stress portrait, ACHE variant, HD R6/1 transgenic, CRTC1 KO, and HTRA2 KO) were analyzed and common up and down regulated genes with depression were identified." (PMID 34997033, 2022). "Vorinostat (SAHA), which inhibits the activity of histone deacetylases HDAC 1–3 and HDAC6, modulates inflammation and oxidative stress by reducing the level of malondialdehyde (MDA) and IL-1ß and the expression of the mRNA of the genes Nfkb1 and Hdac2 in the CORT model of depression." (PMID 35011254, 2021). "Several lines of evidence suggest a key role of HDAC2 in the response to stress and depression." (PMID 34276306, 2021). "In comparison, Mal-gluc can be a promising agent for treating depression since it is capable of penetrating across the BBB and accumulating in the brain, and that Mal-gluc selectively inhibits HDAC2 while sparing other classes of HDACs." (PMID 29396460, 2018). "The CUMS procedures elevated the expression level of HDAC2 and induced the downregulation of acH3K9 protein and BDNF mRNA, and ultimately contributed to depressive disorder." (PMID 29636708, 2018). "Chronic stress enhances the function of HDAC2, which inhibits the transcription of glial cell-derived neurotrophic factor (GDNF) and thus induces depression; abnormal expression of HDAC4/5 and subsequent abnormal acetylation of histones leads to depression." (PMID 37140907, 2023). "A genotype × environment (GxE) animal model of depression showed increased Hdac2 expression in the nucleus accumbens, whereas a GxE animal model of resilience showed no alterations of Hdac2 expression." (PMID 34276306, 2021).
depression (continued). "It should be noted that patients with MDD show increased Hdac2 expression and reduced Gdnf expression in the peripheral blood cells and whole blood, supporting a contribution of the HDAC2–GDNF pathway to the depression." (PMID 34276306, 2021). "We found that the CUMS procedures elevated the expression level of HDAC2 and induced the downregulation of acH3K9 protein and BDNF mRNA, which might contribute to the development of depression." (PMID 29636708, 2018).
glioma (20 papers, 2015 to 2025). A benign or malignant brain and spinal cord tumor that arises from glial cells (astrocytes, oligodendrocytes, ependymal cells). "In addition, HDAC2 is associated with the invasion and drug resistance of glioma cells." (PMID 38985240, 2025). "The CNOT7 was positively correlated with transcription factors TOP2A or HDAC2 in glioma patients’ samples, especially HDAC2 (Spearmen = 0.42, Pearson = 0.41, R2 = 0.17)." (PMID 38985240, 2025). "These evidences revealed that the high-expressed CNOT7 is an oncogene with poor prognosis and participated in the progression of glioma, and HDAC2 upregulated CNOT7 expression." (PMID 38985240, 2025). "We first investigated the expression of HDAC2 in human glioma patients via analysis of the GEPIA and TCGA public databases." (PMID 35260183, 2022). "HDAC2 expression was also significantly correlated with glioma grade and positively correlated with purity infiltration." (PMID 35359455, 2022). "The Oncomine data revealed that compared with normal tissues, the HDAC1/2/3/6 transcriptional levels were significantly elevated and those of HDAC2/4/5/11 were significantly decreased in CNS cancer tissues." (PMID 35359455, 2022). "We evaluated relative mRNA expression levels of HDAC1 and HDAC2 across different grades of glioma using the The Cancer Genome Atlas (TCGA), Chinese Glioma Genome Atlas (CGGA), and Repository of Molecular Brain Neoplasia Data (REMBRANDT) databases." (PMID 34494550, 2021). "The HDAC1 and HDAC2 comparisons in glioma, and the HDAC11 comparison in GBM, were remarkable for their significantly contrasting expression." (PMID 34540896, 2021). "HDAC-related genes upregulated in IDH1/2mut glioma include HDAC2/4/5, KDM1A, CHD4, MTA2/3, SIRT1/2, PHF21A, and BRMS1L." (PMID 34424450, 2021). "We compared HDAC1 and HDAC2 protein expression in gliomas using the Human Proteome Atlas and found that both were strongly expressed in most gliomas, although HDAC1 expression is higher in GBM than in low-grade gliomas." (PMID 34494550, 2021). "It showed that two studies supported significantly overexpressed HDAC2 in CNS cancer, but an equal number of studies concluded otherwise." (PMID 34540896, 2021). "Other clusters with positively co-correlated genes containedPPARGC1B and HDAC11, both strongly down-regulated in gliomas, and HDAC2, HDAC9 andSIRT6." (PMID 25791281, 2015). "HDAC2 plays an important role in the development of glioma by regulating tumor signaling pathways." (PMID 38985240, 2025). "Inhibition of CNOT or HDAC2 is a therapeutic approach for glioma treatment." (PMID 38985240, 2025). "Besides, it was found that the HDAC2 (Human histone deacetylase-2) contributes to increased CNOT7 expression in glioma." (PMID 38985240, 2025). "HDAC2 expression was higher in glioma tumor than in normal tissues." (PMID 35359455, 2022). "The Lee 2006 study recruiting 22 cases of GBM which was larger than the size of the other two HDAC2 studies might suggest that HDAC2 was under-expressed in glioma." (PMID 34540896, 2021). "In contrast, HDAC2 was expressed at high levels across all glioma samples." (PMID 34494550, 2021). "Surprisingly, we find that HDAC1 is the essential class I deacetylase in glioma stem cells, and its loss is not compensated for by HDAC2." (PMID 34494550, 2021). "However, the study size of the three studies was too limited to conclude firmly regarding HDAC2 expression level in glioma." (PMID 34540896, 2021). "However, HDAC2 expressed the most in the WHO III group but the least in the WHO IV group, indicating a baffling part HDAC2 played in the glioma progression." (PMID 34540896, 2021). "Finally, it was found that HDAC2 contributes to increased CNOT7 expression in glioma." (PMID 38985240, 2025).